GATA2 (GATA binding protein 2)
Diseases named in the same sentence as GATA2 in open-access papers (continued):
Sharing a sentence is not in itself a finding about the gene and the disease.
Immunodeficiency (continued). "Otherwise, patients with GATA2 deficiency present variable grade of immunodeficiency and other comorbidity that could threaten the outcome of HSCT with a high rate of transplant related toxicity." (PMID 33066218, 2020). "Distinct clinical perspectives discerned in these studies coalesce under the theme of the loss of one allele of GATA2 resulting in the GATA2 haploinsufficiency syndrome, which can present with immunodeficiency, lymphedema and 80% predisposition to develop MDS/AML." (PMID 34713225, 2020). "Hematologic and immunological phenotypes were consistent with the heterogeneous clinical picture of GATA2 deficiency and included varying degrees of immune cytopenias (low B/NK, DC cells, monocytopenia), immunodeficiency, neutropenia, and/or pancytopenia (supplemental case descriptions)." (PMID 32555368, 2020). "However, with regards to the possible oligogenic etiology of immunodeficiency in GATA-2 deficiency, impact of other genes implicated in EBV control should be considered." (PMID 25879889, 2015). "Although a family history of myeloid malignancies or immunodeficiency may help in the decision to screen for GATA2 variants, it is important to note that GATA2 de novo variants constitute a significant proportion of cases in some phenotypes such as in children or young adults with MDS." (PMID 34387894, 2021). "The study of rare mutations in blood and immune disorders has elucidated novel roles for regulators of hematopoiesis and uncovered numerous important molecular pathways, as seen through examples such as Diamond‐Blackfan anemia and the GATA2 deficiency syndromes." (PMID 31313878, 2019). "GATA2 encodes a hematopoietic cell transcription factor, and mutations may manifest as monocytopenia, dendritic and B cell deficiencies, myelodysplasia, and immunodeficiency." (PMID 26812071, 2016). "Allogenic transplantation of hematopoietic stem cells is currently the only curative method for GATA2-associated MDS/AML and immune dysfunction." (PMID 41322420, 2025). "This study reports a rare case of persistent immunodeficiency in a child with AML and GATA2 mutation after SARS-CoV-2 infection, emphasizing the role of viral infection in immune dysfunction in such patients." (PMID 40797383, 2025). "The manifestation with lymphedema, immunodeficiency with monocytopenia, susceptibility to viral infections and active HPV-infection constitute the hallmarks of GATA2 deficiency in this patient." (PMID 38993648, 2024). "Recently, allogeneic hematopoietic stem cell transplantation resulted in cure of immunodeficiency and EBV+ SMTs in a GATA2-deficient patient." (PMID 29535735, 2018). "In humans, germline heterozygous GATA2 mutations result in pleiotropic manifestations with hematologic cytopenia leading to myelodysplastic neoplasms (MDS); immunodeficiency in multiple cell lineages involving B, NK, monocytic, CD4+, and dendritic cells; and can also lead to deafness and lymphedema." (PMID 41249190, 2025). "GATA2 germline mutations are also reported in patients with myeloid malignancy without evidence of preceding immunodeficiency or other disturbances." (PMID 40725177, 2025). "For AML patients with GATA2 mutation who achieve remission, SARS-CoV-2 infection may still trigger severe and persistent immunodeficiency, leading to serious infections and affecting prognosis." (PMID 40797383, 2025). "Additionally, cases of GATA2 and TACI deficiency presenting with HVLD suggest a potential link to underlying immune dysfunction." (PMID 40191186, 2025). "Consistent with this, mutations within SE regions of other genes, including GATA2, IKZF1, and IRF8, have similarly been implicated in distinct immunodeficiency syndromes by disrupting the development and function of DCs, NK cells, and additional immune subsets." (PMID 40895527, 2025).
Immunodeficiency (continued). "In our patient, WES analysis focusing on a gene panel linked to immunodeficiencies identified two variants (c.1132A>G substitution in GATA2, c.8287_8295dup in CHD7) likely ascribed to have a negative impact on the immune system." (PMID 37959410, 2023). "Importantly, the pattern of immune changes was quite distinct from that seen in GATA2-related immunodeficiency, where profound monocytopaenia is characteristic; all subjects (21 of 21) had normal monocyte counts." (PMID 34916230, 2023). "Therefore, GATA2 deficiency constitutes a unique primary immune deficiency (PID), as it can first manifest in adult life upon an age-related decline in the number of GATA2-deficient HSPCs." (PMID 35603181, 2022). "Germline mutations in GATA2 can lead to GATA2 deficiency characterized by a complex multi-system disorder that can present with many manifestations including variable cytopenias, bone marrow failure, MDS/AML, and severe immunodeficiency." (PMID 36338673, 2022). "Although not with clear association to vascular dysfunction or immune deficiencies, premature labor and miscarriages have been described in GATA2 deficiency and other germline conditions." (PMID 35356204, 2022). "GATA2‐related immunodeficiency is also known as immunodeficiency 21 (MIM# 614172)." (PMID 34387894, 2021). "Hereditary MDS/AML, rather than immune dysfunction, is the principle clinical feature of several kindreds with GATA2 mutation." (PMID 25707267, 2015). "Although the frequency of severe, genital HPV disease in these immunodeficiencies is not well-established given the rarity overall of these disorders, GATA2 haploinsufficiency is unique in that HPV disease may be the first or the earliest phenotypic presentation of immune dysfunction." (PMID 39267745, 2024). "In summary, anti-cytokine autoantibodies have been considered as an important etiology of immunodeficiency, though there are also many immunodeficiencies that do not rely on anti-cytokine autoantibodies, like GATA2 deficiency, one of the most prevalent causes of hereditary bone marrow failure." (PMID 35003106, 2021). "Immunodeficiencies involve SE dysregulation affecting key TFs like BACH2, GATA2, and IKZF1, leading to impaired immune cell development and function." (PMID 40895527, 2025). "Together, these observations show that GATA2 plays a stage‐specific differentiation role not only in the HSC but also the GMP compartment and that germline GATA2 LOF variants in humans may act similarly to predispose to distinct diseases such as MDS/AML, immunodeficiency, and lymphedema." (PMID 34387894, 2021). "The often early age of onset of malignancy, immunodeficiency, or other phenotypes for G2DS and apparent anticipation seen in some GATA2 families may explain a lower level of founder effect and lower predominance of germline GATA2 variants in sporadic adult MDS or AML cohorts compared to DDX41." (PMID 34387894, 2021). "Myeloid neoplasms with episodes suggestive of immunodeficiency/IBD and a marked reduction or absence of B cells, monocytes, NK cells, and dendritic cells should be actively screened for GATA2 variants." (PMID 40821825, 2025). "In the setting of stress hematopoiesis, BM from Gata2+/− mice exhibited a reduction in the abundance and functionality of immunophenotypically defined HSC displaying a phenotype resembling patients with G2DS immunodeficiency." (PMID 34387894, 2021). "Therefore, it is recommended to screen patients with PAP and/or immunodeficiency and/or myeloid malignancies without anti-GM-CSF antibodies for GATA2 alterations." (PMID 36900380, 2023).
prostate carcinoma (61 papers, 2008 to 2026). A carcinoma that arises from epithelial cells of the prostate gland. "For example, the prostate cancer risk SNP rs55714314 (P = 4.86×10−12) was identified in the eRNA region of the GATA2 gene." (PMID 39950845, 2025). "The pioneer TF FOXA1 and GATA2 have been previously linked to the regulation of ABCC4 expression in prostate cancer, where MRP4 has been validated as a clinically relevant prognostic marker associated with metastasis." (PMID 39114357, 2024). "In prostate cancer, increased GATA2 expression associates with tumor progression, and GATA2 has been proposed as a prominent factor in the regulation of androgen receptor-related genes." (PMID 35326649, 2022). "GATA2 was highly susceptible to proteasomal degradation in all benign TA cells in contrast to in LNCaP and 22Rv1 prostate cancer cell lines." (PMID 35203681, 2022). "The pioneer factor GATA2 is a significant prostate cancer (PC) driver and is linked to poor prognosis." (PMID 34636746, 2021). "Accordingly, GATA2 activity in human prostate cancer is strongly associated to AR levels and is hence considered a prostate cancer oncogene." (PMID 29888169, 2018). "GATA2 has been implicated in later-stage, lethal prostate cancers as well." (PMID 36212399, 2022). "We also conducted a detailed examination of the pioneer capacity of GATA2 in regulating dynamical nucleosome reorganization in hormone-induced prostate cancer cells, and further implicated GATA2-mediated Wnt/β-catenin signaling in conferring aggressiveness in prostate cancer." (PMID 35672415, 2022). "The GATA2 gene has been associated with a variety of diseases, including coronary heart disease, Parkinson's disease, and lung, colon, and prostate cancers." (PMID 35372566, 2022). "In addition, the upregulation of GATA2 is associated with chemoresistance in the prostate cancer cell lines DU145 and 22Rv1, and GATA2 expression is likewise highest in CRPC patients treated with chemotherapy." (PMID 36212399, 2022). "In addition, high expression of GATA2 was associated with an increased risk of unfavorable clinical outcomes in patients with prostate cancer after radical prostatectomy." (PMID 34592889, 2021). "High expression of GATA2 is related to high risk of prostate cancer." (PMID 28264478, 2017). "In prostate cancer cell lines, several AR regulators have been identified, including GATA2, HOXB13, FOXA1, and TFAP2C." (PMID 41596366, 2026). "Other prostate cancer-associated somatic mutations were consistent in some PDOs and parental tumours, such as BRCA1, ALK, STED2, TET2, TRPM8, AURKA, ERBB2, GATA2." (PMID 41403018, 2025). "In prostate cancer, we observed that the lead variants are significantly enriched in NKX3-1 (n = 61 genes), followed by GATA2 (n = 13) (Fisher's exact test, P < 0.01 for all)." (PMID 39535029, 2025). "It is noteworthy that GATA2 has been identified as a “pioneer factor” for AR in the prostate cancer epithelial cells, facilitating chromatin accessibility for AR binding and transcriptional regulation." (PMID 40196482, 2025). "In prostate cancer cell lines, Ar expression is promoted by GATA2 while GATA2 expression is repressed by androgen-AR action, forming a negative feedback regulatory loop." (PMID 40196482, 2025). "The tumor volume and weight were lower in GATA2 knockdown groups in comparision to control groups, thereby suggesting that GATA2 promotes prostate cancer cell proliferation in vivo." (PMID 37550764, 2023). "The androgen-responsive expression of TMPRSS2 has been shown to be regulated by GATA2 in prostate cancer cells." (PMID 37208193, 2023). "Despite that previous studies have demonstrated the pioneer functionality of GATA2 in hormone-induced prostate cancer cells, all of these studies emphasized on the pioneering role of GATA2 in activating or enhancing AR-dependent gene transcription." (PMID 35672415, 2022).
prostate carcinoma (continued). "Collectively, our data support a noncanonical pioneer GATA2 model and elicit the pioneer capacity of GATA2 action in hormone-induced prostate cancer cells." (PMID 35672415, 2022). "For instance, GATA2 enhances aggressiveness and resistance to standard therapies against prostate cancer." (PMID 35752837, 2022). "Emerging strategies to therapeutically target GATA2 in prostate cancer include the GATA2 small molecule inhibitor K7174 which suppresses the expression of AR, AR splice variants, and AR target genes via a posttranscriptional mechanism of inhibition." (PMID 36212399, 2022). "Yet, GATA2 was found to regulate a set of AR-independent genes in a castration-resistant and chemotherapy-resistant xenograft model of prostate cancer." (PMID 36212399, 2022). "GATA2 has been shown to be an important transcription factor together with androgen receptor (AR) in prostate cancer cells." (PMID 35203681, 2022). "GATA2 has been reported to directly upregulate IGF2 in chemo-resistant prostate cancer, while IGF2 activity leads to PAX2 overexpression in Wilms’ tumor, suggesting a possible signalling axis in NET-PATZ1." (PMID 34417833, 2021). "The oncogenic role of GATA2 has been validated in prostate cancer, which enhances the invasiveness, dissemination, and survival of cancer cells." (PMID 34592889, 2021). "Treatment of prostate cancer cells with enzalutamide enhances recruitment of pioneer factor GATA2, AR, Mediator subunits MED1 and MED14, and RNA Pol II to regulatory elements of enzalutamide-responsive genes." (PMID 31501863, 2019). "Among these factors, GATA2 and FoxA1 play particularly essential roles in androgen receptor signaling in prostate cancer cells." (PMID 31552182, 2019). "On the cellular level, GATA2 overexpression in prostate cancer cells increases their proliferation, motility and invasiveness." (PMID 31357971, 2019). "More recent studies have revealed that GATA1 and GATA2 also participate in the progression of breast cancer and prostate cancer via EMT processes." (PMID 30872657, 2019). "Inhibition of GATA2 by small-molecule compounds is a potential strategy in blocking AR expression and signaling in castration-resistant prostate cancer." (PMID 31552182, 2019). "Whilst FOXA1 represses AR binding to DNA, GATA2 positively collaborates with the AR in androgen-mediated gene expression in prostate cancer." (PMID 28264478, 2017). "GATA2 is required for AR binding in prostate cancer cells, whereas GATA3 is necessary for ER mediated gene expression in breast cancer." (PMID 28264478, 2017). "GATA2 has roles in development and has recently been ascribed various roles in prostate cancer development." (PMID 28038451, 2017). "In cultured prostate cancer cell lines, GATA2 has been shown to function as a pioneer factor for AR genomic binding and function, while surprisingly GATA3 is not expressed." (PMID 27374105, 2016). "In cultured prostate cancer cells, GATA2 regulates AR gene expression and also acts as a pioneer factor to cooperate with AR to regulate AR target gene expression." (PMID 27374105, 2016). "It has been established that AR transactivation of target genes in cultured prostate cancer cells requires pioneer factors, such as FoxA1 and GATA2." (PMID 27374105, 2016). "In cultured prostate cancer cells, GATA2 coordinates with androgen receptor (AR) to regulate gene transcription." (PMID 27374105, 2016). "In cultured prostate cancer cells, GATA2 is essential for the expression of a subset of AR target genes such as PSA and NKX3.1." (PMID 27374105, 2016). "In prostate cancer, GATA2 plays a crucial role in mediating androgen receptor (AR) expression, as well as in site-specific AR recruitment facilitating AR target gene expression." (PMID 26287967, 2015). "These include associations between 1-monoolein and GATA2, a key regulator of hematopoiesis, or SLC45A3, a known diagnostic marker for prostate cancer." (PMID 26086077, 2015).
prostate carcinoma (continued). "The finding suggests that GATA2 plays a critical role in the homeostasis of prostate cancer cell transcriptomes." (PMID 24448395, 2014). "Follow-up experiments on the genes of the brown module appear to be warranted to get further insight into the role of the GATA2 gene in prostate cancer metastasis." (PMID 24448395, 2014). "We focussed on GATA2 as a potential prostate cancer metastasis-driving gene, since this gene is well known as a master regulatory gene in the hematopoietic system with a role in tumorigenesis." (PMID 24448395, 2014). "Further evidence for the GATA2 gene being an important regulatory gene in prostate cancer is the finding that the silencing of the GATA2 gene in LNCaP cells led to significantly changed expression of as many as 2400 genes (>2 fold change, FDR <0.05)." (PMID 24448395, 2014). "Elevated GATA2 expression in metastatic prostate cancer tissues correlated with poor patient prognosis." (PMID 24448395, 2014). "The pioneer factors FoxA1 and GATA2 are recruited to a significant portion of AR-binding sites in prostate cancer cells, facilitating AR binding to AREs by interacting directly with AR and consequently enhancing AR-mediated transcription." (PMID 23887938, 2013). "In both hormone-dependent breast and prostate cancers, FOXA1 forms a triumvirate with a GATA protein and an NR (GATA3 and ER in breast cancer; GATA2 and AR in prostate cancer) and is the foundational protein in these cancers due to its ability to create new enhancer elements." (PMID 41168397, 2025). "GATA2 and GATA3 are known AR co-regulators in prostate cancer but any race-specific association is unknown." (PMID 38566104, 2024). "Moreover, in prostate cancer, GATA2 has been well-characterized as a critical pioneer TF for AR, whereas GATA2 can mediate PTX resistance by AR-independent regulation of IGF2." (PMID 38126976, 2023). "Our results indicated that GATA2-upregulated ST6GALNAC5 might serve as an adverse prognostic biomarker promoting prostate cancer cell invasion." (PMID 37468844, 2023). "Importantly, GATA2 regulates the metastatic potential of prostate cancer cells in the early stages of disease." (PMID 36980710, 2023). "Thus, as is the case during HSPC, GATA2 contributes to prostate cancer growth during CRPC by amplifying the AR transcriptional program." (PMID 36212399, 2022). "Moreover, recent studies confirmed that GATA2 overexpression in prostate cancer increases cellular motility and invasiveness, proliferation, tumorigenicity, and resistance to standard therapies." (PMID 35488350, 2022). "GATA2 interacts with androgen receptor to modulate gene transcription in prostate cancer cells." (PMID 35752837, 2022). "Finally, GATA2, another pioneer transcription factor, is crucial for the activation of AR signaling in prostate cancer." (PMID 36212399, 2022). "Nevertheless, it can be concluded that GATA2 has restricted expression in benign prostate cells due to proteolytic degradation of GATA2-wt in contrast to the prostate cancer cell lines LNCaP and 22Rv1, and also in contrast to benign human kidney embryonal cells." (PMID 35203681, 2022). "Our work may provide a rationale for targeting GATA2 downstream signaling as a therapeutic strategy to treat advanced prostate cancer." (PMID 35672415, 2022). "However, in the prostate cancer cell lines, Gata2 is one of the transcription factors that regulates Ar expression." (PMID 35025767, 2022). "GATA2 was reported to function early in hematopoiesis 38 and was lowly expressed in several tumors, such as hepatocellular carcinoma 39, gastric cancer 40, clear cell renal cell carcinoma 35, and highly expressed in prostate cancer." (PMID 34093794, 2021). "Additionally, GATA2 is identified as a poor prognosis marker in colorectal cancer, prostate cancer and hepatocellular cancer." (PMID 30872657, 2019).